NCOA4 (nuclear receptor coactivator 4)
Diseases named in the same sentence as NCOA4 in open-access papers (continued):
Sharing a sentence is not in itself a finding about the gene and the disease.
kidney stone (2 papers, 2021 to 2025). "In animal models of kidney stones, upregulated NCOA4 expression and increased iron pools are closely associated with tubular injury, potentially contributing to the formation of a lithogenic microenvironment." (PMID 40909330, 2025). "To verify whether the ferroptosis caused by excessive autophagy in the kidney stone model is related to the abnormal expression of NCOA4, we detected the expression of NCOA4 by immunohistochemistry and western blotting in cell and animal models of stone formation." (PMID 34659638, 2021). "In the early stages of nephrolithiasis, Beclin-1/ATG6 (BECN1)-nuclear receptor coactivator 4 (NCOA4)-mediated ferritinophagy disrupts iron homeostasis, resulting in iron overload." (PMID 40909330, 2025). "According to previous studies, both autophagy and ferroptosis play an important role in the formation of kidney stones; however, it has not been determined whether there is a relationship between them and whether NCOA4 plays an important role in this relationship." (PMID 34659638, 2021).
lung diseases (2 papers, 2021 to 2026). "Our findings reveal that KF mitigates COPD progression by coordinately targeting the Nrf2/NCOA4/GPx4 axis to inhibit ferroptosis, providing a novel therapeutic strategy for oxidative stress‐driven pulmonary diseases." (PMID 41474210, 2026). "Our findings not only elucidate the Nrf2/NCOA4/GPx4 axis as a previously unrecognised mechanism through which kaempferol counteracts smoke‐induced ferroptosis in COPD, but also highlight its potential as a multitarget phytotherapeutic agent for combating oxidative stress‐driven pulmonary diseases." (PMID 41474210, 2026).
melanoma (2 papers, 2024 to 2025). A malignant, usually aggressive tumor composed of atypical, neoplastic melanocytes. "BNIP3 deficiency induces NCOA4-mediated ferritinophagy, with PHD2-mediated HIF-1α downregulation inhibiting tumor glycolysis and growth in BNIP3-silenced melanoma cells." (PMID 41298345, 2025). "In melanoma cells, BNIP3 deficiency results in increased intracellular iron levels caused by heightened nuclear receptor coactivator 4 (NCOA4)-mediated autophagic degradation of ferritin (ferritinophagy), which facilitates HIF-1α degradation." (PMID 38674050, 2024).
osteoarthritis (2 papers, 2024 to 2025). A noninflammatory degenerative joint disease occurring chiefly in older persons, characterized by degeneration of the articular cartilage, hypertrophy of bone at the margins and changes in the synovial membrane. "Besides, it has been revealed that the JNK-JUN axis exacerbates osteoarthritis (OA) by regulating NCOA4-mediated ferroptosis and inhibiting the JNK-JUN-NCOA4 axis can mitigate OA development in mice." (PMID 39744165, 2025).
renal carcinoma (2 papers, 2022). A carcinoma arising from the epithelium of the renal parenchyma or the renal pelvis. "Concurrently, inhibiting the degradation of NCOA4, enhancing the level of ferritinophagy, and promoting the occurrence of ferroptosis in renal cancer cells can provide a theoretical basis for the treatment of renal cancer." (PMID 36755884, 2022). "Recent studies suggest that nuclear receptor coactivator 4 (NCOA4) may be a predictive biomarker for renal cancer." (PMID 35756082, 2022).
salivary gland carcinoma (2 papers, 2017 to 2025). A carcinoma that arises from the major or minor salivary glands. "Additionally, fusions observed in other subtypes of salivary gland carcinoma, such as ETV6::NTRK3 and NCOA4::RET described in secretory carcinoma and intraductal carcinoma, respectively, have been reported in SDC without any histologic evidence of these other tumor types." (PMID 41357819, 2025).
Age-related cataract (1 paper, 2024). A type of cataract (opacification of the lens) that forms during the course of aging. "A recent study reported that melatonin suppresses ferroptosis by regulating the SIRT6/p-Nrf2/GPX4 and SIRT6/NCOA4/FTH1 pathways in age-related cataract." (PMID 39519165, 2024).
Allergy (1 paper, 2022). An allergy is an immune response or reaction to substances that are usually not harmful. "Though best known in allergy and anaphylaxis, the TME mast cells highly express immunosuppressive IL6R and ferroptosis-related signatures including PEBP1 and NCOA4." (PMID 36148946, 2022).
Alzheimer disease (1 paper, 2024). A progressive, neurodegenerative disease characterized by loss of function and death of nerve cells in several areas of the brain leading to loss of cognitive function such as memory and language. "Prior research confirmed that the occurrence of ferroptosis in the Alzheimer’s disease mouse model was accompanied by a significant decrease in SLC7A11, SLC3A2, and FTH1 and an increase in the protein expression of DMT1 and NCOA4." (PMID 39635435, 2024).
benign prostatic hyperplasia (1 paper, 2016). A non-cancerous nodular enlargement of the prostate gland. "The transcript levels of MSMB, nuclear receptor co-activator 4 (NCOA4) and MSMB-NCOA4 fusion were examined by qRT-PCR in prostatectomy samples and by RNA-sequencing in benign prostatic hyperplasia, PC, and CRPC samples." (PMID 26939004, 2016).
bile duct cancer (1 paper, 2025). "The experimental results in this manuscript illustrate that NCOA4 is primarily involved in the invasion and migration of bile duct cancer cells, and the inhibition of NCOA4 expression promotes the migration and invasion potential of bile duct cancer cells." (PMID 40788949, 2025).
cardiac arrest (1 paper, 2025). Cessation of breathing and/or cardiac function. "Consequently, we hypothesize that following cardiac arrest and CPR, NCOA4-mediated ferritinophagy is activated while FPN1 expression is reduced, leading to iron accumulation." (PMID 39984437, 2025).
demyelination (1 paper, 2023). "We recently showed a rapid and transient increase in expression of NCOA4 in oligodendrocytes, in the cuprizone-induced demyelination model." (PMID 37491291, 2023).
diabetic cardiomyopathy (1 paper, 2025). Diabetic cardiomyopathy is a disorder of the heart muscle in people with diabetes. "However, to date, no studies have examined the role of ALA in regulating NCOA4-mediated ferritinophagy in the context of cardiac injury associated with diabetic cardiomyopathy." (PMID 41515376, 2025).
Encephalopathy (1 paper, 2022). Encephalopathy is a term that means brain disease, damage, or malfunction. "Our study revealed that the pathophysiology of static encephalopathy of childhood with neurodegeneration in adulthood/β-propeller protein-associated neurodegeneration involves ferrous iron insufficiency via impaired ferritinophagy through nuclear receptor coactivator 4 expression reduction." (PMID 36751498, 2022).
esophageal squamous cell carcinoma (1 paper, 2025). Esophageal squamous cell carcinoma (ESCC) is a type of esophageal carcinoma (EC) that can affect any part of the esophagus, but is usually located in the upper or middle third. "In esophageal squamous cell carcinoma, hypoxia inhibits ferritinophagy-mediated ferroptosis through the USP2 (ubiquitin specific peptidase 2)-NCOA4 (nuclear receptor coactivator 4) axis." (PMID 39935430, 2025).
Fanconi anemia complementation group D2 (1 paper, 2022). Fanconi anemia caused by mutations of the FANCD2 gene. "Furthermore, genes associated with autophagy, such as nuclear receptor coactivator 4 (NCOA4) and fanconi anemia complementation group D2 (FANCD2), have also been discovered as key regulators of ferroptosis." (PMID 36406272, 2022).
gestational diabetes mellitus (1 paper, 2023). "In gestational diabetes mellitus (GDM), circHIPK3 blocks miR-1278 to enhance DNMT1 expression and facilitates ferroptosis by inducing NCOA4-mediated ferritinophagy." (PMID 37686142, 2023).
goiter (1 paper, 2024). Enlargement of the thyroid gland usually caused by lack of iodine in the diet, hyperthyroidism, or thyroid nodules. "NCOA4 fusion was associated with patients’ sex, multifocality, microcarcinoma character, medical history of goiter, and obstructive pulmonary disease, while SQSTM1 fusion was linked with multifocality and medical history of thyroid/parathyroid adenoma." (PMID 39409115, 2024). "NCOA4 fusion correlated with sex, multifocality, microcarcinoma character, history of goiter, and obstructive pulmonary disease." (PMID 39409115, 2024). "Moreover, the patient’s sex, comorbidities such as goiter and obstructive pulmonary disease, or histological features like microcarcinoma, two-sidedness, and multifocality tended to cluster with the NCOA4 fusion gene." (PMID 39409115, 2024).
Granuloma (1 paper, 2023). A compact, organized collection of mature mononuclear phagocytes, which may be but is not necessarily accompanied by accessory features such as necrosis. "By quantifying the percentages of NCOA4-positive macrophages within non-necrotizing and necrotizing granulomas, we observed a higher percentage of NCOA4-positive macrophages in the therapeutic resection tissues than in the diagnostic biopsy specimens." (PMID 37066876, 2023).
H1N1 virus infection (1 paper, 2024). "In NC cells, FTH1 fluorescence was significantly attenuated after PR8 H1N1 virus infection, and silencing NCOA4 significantly inhibited the attenuation of FTH1 fluorescence." (PMID 39159143, 2024). "NCOA4 KO significantly inhibited FTH1 degradation after PR8 H1N1 virus infection." (PMID 39159143, 2024). "In CQ‐treated NPTr cells, the degradation of NCOA4 and FTH1 was significantly inhibited after HuB H1N1 virus infection compared to the control." (PMID 39159143, 2024). "Consistent with the results in A549 cells, the protein expression of NCOA4 and FTH1 was significantly decreased at 12, 24, and 36 hpi after HuB H1N1 virus infection." (PMID 39159143, 2024).
heart failure (1 paper, 2021). Inability of the heart to pump blood at an adequate rate to meet tissue metabolic requirements. "Further studies are necessary to elucidate molecular mechanism underlying NCOA4-mediated cardiomyocyte death and heart failure." (PMID 33526170, 2021). "Cardiomyocyte-specific Ncoa4 ablation attenuated the development of pressure overload-induced heart failure." (PMID 33526170, 2021). "It is also possible that NCOA4 may associate with NRF2/HO-1 and VDACs-induced mitochondrial dysfunction pathways in ferroptosis-induced cardiomyocytes death and heart failure." (PMID 33526170, 2021).
hereditary hemochromatosis (1 paper, 2022). An inherited metabolic disorder characterized by iron accumulation in the tissues. "Thus, pharmacologically modulating autophagy or more specifically NCOA4-mediated ferritinophagy could be relevant to treatment of disorders of systemic iron dyshomeostasis, including anemia of inflammation and hereditary hemochromatosis." (PMID 36290647, 2022).
Huntington disease (1 paper, 2024). Huntington disease (HD) is a rare neurodegenerative disorder of the central nervous system characterized by unwanted choreatic movements, behavioral and psychiatric disturbances and dementia. "A growing number of evidence has implicated NCOA4‐mediated ferritinophagy to be a major cause of the pathogenesis of neurodegenerative disorders, including Alzheimer's disease (AD), PD, Huntington's disease and amyotrophic lateral sclerosis." (PMID 38389491, 2024).
hyperandrogenism (1 paper, 2025). Excessive secretion of androgens from the adrenal glands or gonads. "Hyperandrogenism-Ferroptosis Cycle: Dihydrotestosterone (DHT) upregulates factors like NCOA4, forming a self-amplifying pathological loop unique to PCOS." (PMID 41479924, 2025).
Hypertension (1 paper, 2025). The presence of chronic increased pressure in the systemic arterial system. "YTHDF2 knockdown and NCOA4 overexpression acted synergistically to exacerbate ferroptosis, both in trophoblasts and in a PE mouse model, leading to aggravated hypertension, proteinuria, and fetal growth restriction, which were partially reversed by Fer-1." (PMID 41257944, 2025).
hyperuricemia (1 paper, 2025). An abnormally high level of uric acid. "We verified that hyperuricemia activated autophagy‐dependent ferritinophagy by using the autophagy inhibitor chloroquine in combination with Bodipy C11 staining and detecting the iron‐autophagy protein NCOA4 and the autophagy marker LC3II." (PMID 40041973, 2025).
infertile (1 paper, 2022). "Hence, the presence of iron overload in the FF of infertile patients with EMs can promote NCOA4 expression within granulosa cells, leading to active ferritinophagy, which further contributes to the development of ferroptosis by enhancing lipid peroxidation in granulosa cells." (PMID 35787614, 2022).
Insulin resistance (1 paper, 2024). Increased resistance towards insulin, that is, diminished effectiveness of insulin in reducing blood glucose levels. "Supplementation with ferric ammonium citrate or ferric agents improved hepatic insulin resistance and ER stress by regulating the expression of NCOA4 and ferritin." (PMID 38961066, 2024).
intervertebral disc degeneration (1 paper, 2023). "The immunofluorescence results indicate a significant increase in the expression levels of NCOA4 and PCBP1 proteins, while the expression level of GPX4 protein was decreased in human intervertebral disc degeneration tissues." (PMID 37736497, 2023).
invasive breast carcinoma (1 paper, 2012). A carcinoma that infiltrates the breast parenchyma. "Since AR is a favorable prognostic indicator, and its action in breast epithelium generally leads to inhibition of cell growth, loss of NcoA4 and/or AR in the presence of Her2/neu could represent more aggressive subtypes of invasive breast cancer." (PMID 22562579, 2012).
ischemia (1 paper, 2025). A hypoperfusion of the BLOOD through an organ or tissue caused by a PATHOLOGIC CONSTRICTION or obstruction of its BLOOD VESSELS, or an absence of BLOOD CIRCULATION. "Ferritin-bound iron is released into LIP by nuclear receptor coactivator 4 (NCOA4) dependent auto-phagosome degradation, activated during ischemia." (PMID 41154466, 2025).
Leydig cell tumor (1 paper, 2024). A sex cord-stromal tumor occurring in the testis and rarely in the ovary. "Higher TfR1 and NCOA4 expressions were noted in Leydig cell tumors and diffuse seminomas, indicating a reliance on iron for tumor growth." (PMID 39272404, 2024).
metastasis (1 paper, 2023). The spread or migration of cancer cells from one part of the body (where they first appeared) to another. "In term of clinicopathological markers, the NCOA4::RET rearrangement was significantly associated with angioinvasion (p = 0.001), lymphatic invasion (p = 0.003), extrathyroidal extension (p = 0.001), lymph node metastasis (p < 0.001) and extranodal extension (p = 0.013), respectively." (PMID 37188126, 2023).
metastatic colorectal cancer (1 paper, 2015). "Through comprehensive genomic profiling we prospectively identified 6 RET fusion kinases, including two novel fusions of CCDC6-RET and NCOA4-RET, in metastatic colorectal cancer (CRC) patients." (PMID 26078337, 2015).
metastatic tumors (1 paper, 2022). "NCOA4-RET and TRIM27-RET are characteristic gene fusions in salivary Intraductal carcinoma, including invasive and metastatic tumors: is “Intraductal” correct?" (PMID 36227346, 2022).
Miscarriage (1 paper, 2025). A pregnancy that ends at a stage in which the fetus is incapable of surviving on its own, defined as the spontaneous loss of a fetus before the 22th week of pregnancy. "Suppression of lnc-HZ06 or NCOA4 significantly reduced ferroptosis and alleviated miscarriage in hypoxia-exposed animal models, underscoring potential therapeutic strategies for addressing unexplained RM by targeting ferroptosis-driven cellular dysfunction." (PMID 40552306, 2025). "Suppression of lnc-HZ06 and NCOA4 mitigates hypoxia-induced ferroptosis, reducing miscarriage in animal models." (PMID 40552306, 2025).
multinodular goiter (1 paper, 2023). Nodular goiter characterized by more than one discrete tissue mass. "Results from qRT-PCR showed the absence of CCDC6::RET or NCOA4::RET rearrangements in normal tissues (n = 10) and benign (multinodular goiter, n = 10) cases." (PMID 37188126, 2023).
neuroblastoma (1 paper, 2023). Neuroblastoma (NB) is the most common solid, extracranial childhood tumor. "A recent proteomic study revealed that upregulation of ATG7 was accompanied by the upregulation of ferritinophagy-related proteins, such as LC3, ferritin (FTL, FTH1), and NCOA4 in an arsenic trioxide-treated neuroblastoma cell line." (PMID 37522124, 2023).
osteoblastic osteosarcoma (1 paper, 2025). A conventional osteosarcoma characterized by the predominance of osteoid matrix. "In this study we evaluated the immunohistochemical expression of ferritinophagy-related proteins, namely Ferritin Heavy chain (FTH1) and NCOA4, and proliferating cell nuclear antigen (PCNA) in canine normal bone and canine osteoblastic osteosarcoma (COOS) samples." (PMID 40196812, 2025).
ovarian tumor (1 paper, 2018). "We additionally identified increased NCOA4 expression in ovarian tumors (serous, serous papillary, and mucinous) compared to adjacent normal tissues via tissue microarray analyses." (PMID 29435183, 2018). "Immunohistochemical staining for NCOA4 revealed that it was significantly increased in a subset of ovarian tumors relative to normal adjacent tissues: 1) serous adenocarcinoma (total, moderate, and weak positive), 2) serous papillary (moderate and weak positive), and 3) mucinous (weak positive)." (PMID 29435183, 2018).
prostate adenocarcinoma (1 paper, 2016). "Second, the detection of MSMB, NCOA4 and MSMB-NCOA4 fusion transcripts was assessed using RNA-seq in two cohorts; one containing 12 BPH, 28 hormone-naïve PC, and 13 CRPC samples, as well as a second TCGA-cohort consisting of 301 prostate adenocarcinoma tumors." (PMID 26939004, 2016).
prostate intraepithelial neoplasia (1 paper, 2019). A neoplastic proliferation of the epithelial cells that line the acini and the ducts of the prostate gland. "Some studies have reported decreased NCOA4 expression in both prostate intraepithelial neoplasia and malignant prostate when compared to benign prostate, which is consistent with our result of analysis on TCGA dataset." (PMID 31323811, 2019).
psoriasis (1 paper, 2022). An autoimmune condition characterized by red, well-delineated plaques with silvery scales that are usually on the extensor surfaces and scalp. "Some important ferroptosis driver genes, such as RPL8, NCOA4, and ALOXE3, are expressed at low levels in the keratinocyte population in psoriasis." (PMID 35962439, 2022).
rectal cancer (1 paper, 2025). A primary or metastatic malignant neoplasm that affects the rectum. "NCOA4 has been shown to play a regulatory role in the malignant biological behavior of breast, prostate, pancreatic, and rectal cancers." (PMID 40788949, 2025).
renal fibrosis (1 paper, 2025). A final common manifestation of a wide variety of chronic kidney diseases characterized by glomerulosclerosis and tubulointerstitial fibrosis. "Co-exposure to arsenic (As) and PS-NPs causes mitochondrial oxidative damage, ferritinophagy, and ferroptosis, mediated by NCOA4 and mtROS, leading to renal fibrosis." (PMID 41303677, 2025).
salmonellosis (1 paper, 2024). Infections with bacteria of the genus salmonella. "Together, this study not only advances our understanding of NCOA4/KEAP1/NRF2/ferroptosis axis but also paves the way for novel myeloid cell-targeted therapies to combat salmonellosis." (PMID 38798412, 2024). "Nuclear receptor co-activator 4 (NCOA4) regulates iron release via FTH1 degradation during low iron, but its role in salmonellosis is unclear." (PMID 38798412, 2024).
sarcoma (1 paper, 2020). A usually aggressive malignant neoplasm of the soft tissue or bone. "Interestingly, NCOA4 and SLC48A1 are also included in the multigene signature for DFS, which implies that these two genes may play a more important role in the progression of sarcomas." (PMID 33489900, 2020).